NTN1 (netrin 1)
Description:
Netrins control guidance of CNS commissural axons and peripheral motor axons. Its association with either DCC or some UNC5 receptors will lead to axon attraction or repulsion, respectively. Binding to UNC5C might cause dissociation of UNC5C from polymerized TUBB3 in microtubules and thereby lead to increased microtubule dynamics and axon repulsion. Involved in dorsal root ganglion axon projection towards the spinal cord. It also serves as a survival factor via its association with its receptors which prevent the initiation of apoptosis. Involved in tumorigenesis by regulating apoptosis.
Synonyms: NTN1L; NET1; MRMV4
Tractability: Small molecule: a structure with a bound ligand is known. Antibody: UniProt places it where antibodies can reach, with high confidence; its Gene Ontology location is reachable by antibodies, with high confidence; UniProt predicts a signal peptide or a membrane-spanning region.
Gene: Protein-coding gene on chromosome 17 (9,021,210 to 9,244,000, forward strand). Ensembl gene ENSG00000065320.
Subcellular location: Secreted; Cytoplasm
Subcellular location (Human Protein Atlas): Cytosol; Actin filaments; Nucleoplasm; Predicted to be secreted
Pathways (Reactome):
Developmental Biology: DCC mediated attractive signaling; DSCAM interactions; Netrin mediated repulsion signals; Netrin-1 signaling; Regulation of commissural axon pathfinding by SLIT and ROBO; Role of second messengers in netrin-1 signaling
Gene Ontology:
Molecular function: protein binding; DNA-binding transcription factor activity, RNA polymerase II-specific; RNA polymerase II cis-regulatory region sequence-specific DNA binding
Biological process: Cdc42 protein signal transduction; chemorepulsion of axon; positive regulation of axon extension; positive regulation of cell motility; Ras protein signal transduction; regulation of transcription by RNA polymerase II; substrate-dependent cell migration, cell extension; regulation of synapse assembly
Cellular component: cytoplasm; cytosol; extracellular region; RNA polymerase II transcription regulator complex; basement membrane; glutamatergic synapse; synapse
Genetic constraint (gnomAD): Loss-of-function variants: 11 observed, 41.05 expected, observed/expected ratio (o/e) 0.27, 90% interval 0.17 to 0.44. The upper end of that interval is the gene's LOEUF score, 0.44, which puts it in group 1 of 6, group 1 being the genes least tolerant of losing a copy. Missense variants: 733 observed, 776.87 expected, observed/expected ratio (o/e) 0.94, 90% interval 0.89 to 1. Synonymous variants: 371 observed, 328.65 expected, observed/expected ratio (o/e) 1.13, 90% interval 1.04 to 1.23.
Homologues: Orthologues: chimpanzee NTN1 (100% identical), dog NTN1 (99% identical), macaque NTN1 (99% identical), mouse Ntn1 (99% identical), rat Ntn1 (98% identical), tropical clawed frog NTN1 (87% identical), zebrafish ntn1b (81% identical), pig NTN1 (79% identical), rabbit NTN1 (75% identical), Caenorhabditis elegans unc-6 (52% identical), Drosophila melanogaster NetA (52% identical), Drosophila melanogaster NetB (52% identical). Paralogues in human: NTN3 (53% identical), LAMC1 (37% identical), NTN5 (35% identical), LAMC3 (34% identical), LAMA5 (30% identical), LAMA2 (30% identical), LAMA3 (30% identical), LAMB1 (29% identical), LAMB4 (29% identical), LAMA1 (29% identical), LAMB2 (29% identical), NTN4 (27% identical), and 15 more.
Diseases named in the same sentence as NTN1 in open-access papers:
NTN1 is named in the same sentence as 270 diseases in open-access papers, as found by Europe PMC text mining. Sharing a sentence is not in itself a finding about the gene and the disease. The quoted sentences say what the papers report.
colorectal cancer (80 papers, 2005 to 2025). A primary or metastatic malignant neoplasm that affects the colon or rectum. "A study conducted in individuals with inflammatory bowel disease demonstrated that NTN1 is upregulated in fibroblasts associated with colorectal cancer promoting cancer cell stemness, thereby enhancing cancer cell progression." (PMID 40051609, 2025). "Netrin-1, a chemoattractant expressed by floor plate cells, and one of its receptors (deleted in colorectal cancer) has been associated with pronociceptive actions in a number of pain conditions." (PMID 35743067, 2022). "Recently, colon and lung cancer-associated fibroblasts have been shown to produce netrin-1, which enhances the tumorigenicity of cocultured lung cancer and colorectal cancer cells." (PMID 33883596, 2021). "However, the roles of different genes within the Netrin family can be paradoxical, with NTN1 being upregulated in colorectal cancer-associated fibroblast cells and promoting cancer cell stemness." (PMID 37345154, 2023). "Several previous studies have linked netrin-1 signaling in cardioprotection from ischemia and reperfusion injury, for example via interaction of netrin-1 with the classic netrin-1 receptor deleted in colorectal cancer DCC expressed on endothelial cells." (PMID 36247475, 2022). "To characterize the signaling mechanism underlying netrin-1’s effects on vascular function, we assessed levels of its receptor ‘deleted in colorectal cancer’ (DCC) and components of its downstream pathway in aortic tissues from non-diabetic and diabetic WT and Tg3 mice." (PMID 29059224, 2017). "Interestingly, netrin-1 has been shown to be upregulated in a sizeable fraction of metastatic breast, lung, ovary and pancreatic cancer, in inflammatory-associated-colorectal cancer and in neuroblastoma." (PMID 24293316, 2013). "Interestingly, a recent study revealed that NTN1 expression is selectively up-regulated in colorectal cancers associated with bowel diseases." (PMID 21789787, 2011). "JAM-C and Par-3 can also exist in a complex with Deleted in colorectal cancer (Dcc), a transmembrane receptor for guidance cues such as Netrin-1 (Ntn1) which can mediate attraction or repulsion." (PMID 40801950, 2025). "Within this context, the axon guidance signaling mechanism involves Netrin 1 (NTN1) and its receptors Deleted in Colorectal Cancer (DCC) and Unc-5 Netrin Receptor C (UNC5)." (PMID 38540364, 2024). "Netrin-1 protein expression is increased in tissues of many types of cancer such as colorectal cancer (from inflammatory bowel diseases), metastatic breast cancer, non-small cell lung cancer, neuroblastoma, melanoma." (PMID 38638604, 2024). "The receptor mediating Netrin-1-induced neuronal sprouting, deleted in colorectal cancer (DCC), was found to co-localize with CGRP+ sensory nerve fibers in endplates after LSI surgery." (PMID 37961590, 2024). "NTN1 is a pleiotropic secretory glycoprotein that functions as a ligand for two dependence receptors: deleted in colorectal cancer (DCC) and uncoordinated-5 homolog (UNC-5H)." (PMID 37446017, 2023). "To elucidate the mechanisms contributing to CC progression during obesity, we studied the expression of NTN1 and its receptors in VAT and the effect of ACM and NTN-1 on colorectal cancer cell migration." (PMID 36831381, 2023). "The most common receptors of netrin-1 include those deleted in the colorectal cancer family (DCC) and the Unc5 homologous family." (PMID 36647161, 2023). "Multiple guidance cues, such as netrin‐1 (NTN‐1)/deleted in colorectal carcinoma (DCC), control the guidance of axons and help establish functional neural circuits during development." (PMID 36852451, 2023). "The study finally found that the lncRNA PCAT1 derived from colorectal cancer acts as the ceRNA of miR-329-3p to regulate Netrin-1 in CTCs to promote the EMT process and affect the liver metastasis of colorectal cancer." (PMID 36093435, 2022).
colorectal cancer (continued). "Mechanistically, it was discovered that a portion of colorectal cancers exhibit a netrin-1 increase concurrent with transcription factor NF-kB activation and that netrin-1 is a direct transcriptional target of NF-kB." (PMID 36499024, 2022). "Previous studies demonstrated that both Myosin X and Trio interact with DCC (deleted in colorectal cancer), a receptor of Netrin-1, and the Rac1 activation elicited by Netrin-1 is lost in the Trio-deficient cortex." (PMID 34914033, 2022). "Overexpression of netrin-1 has been observed in many types of advanced cancers, such as neuroblastoma, colorectal cancer, pancreatic cancer and hepatic cancer." (PMID 35974411, 2022). "Netrin-1 (Ntn1) and its receptor “Deleted in colorectal carcinoma” have been shown to attract the tip of a sprouting axon in vitro and promote peripheral nerve regeneration, as well as Schwann cell proliferation and migration." (PMID 35573254, 2022). "The importance of netrin-1 was shown in human tumors, such as brain tumors, neuroblastomas, prostate cancer, pancreatic cancer, and colorectal cancer." (PMID 35008701, 2021). "In colorectal cancer, for example, the upregulation of netrin-1 and its receptor UNC5B correlates with the number of cancer-associated fibroblasts (CAFs)." (PMID 35008701, 2021). "Focusing on the mHb, the first step of the mHb axons is to grow dorsoventrally, presumably repulsed by semaphorins from the diencephalic alar plates and then attracted by a netrin 1–deleted in colorectal cancer (Ntn1–Dcc) interaction from the ventral region." (PMID 34169076, 2021). "For example, although netrin-1 promotes the development, spread, metastasis, and stemness of breast cancer, colorectal cancer, and glioma cells, BMP signaling reciprocally suppresses these cancer cell types and processes, at least under some circumstances." (PMID 33883596, 2021). "Netrin 1 (NTN1) and deleted in colorectal carcinoma (DCC) regulate midline zipper glia (MZG) morphology and spatial distribution." (PMID 33871356, 2021). "In particular, netrin-1 up-regulation has been observed to be the way to gain survival advantage for several cancers, such as colorectal cancer, neuroblastoma, glioblastoma and metastatic breast cancer." (PMID 32545553, 2020). "Netrin-1 and its receptor “deleted from colorectal cancer” (DCC) have also been confirmed as potential guidance factors." (PMID 32581730, 2020). "Netrin-1 is a prototypical guidance cue that binds to deleted in colorectal cancer (DCC), and it has been proposed that the guidance cue Draxin modulates this interaction." (PMID 29503192, 2018). "Netrin-1 plays a key role in axon guidance through binding to its receptor, Deleted in Colorectal Cancer (DCC)." (PMID 29479476, 2018). "Binding of extracellular netrin-1 to its receptors, deleted in colorectal cancer (DCC) and uncoordinated gene 5H2 (UNC5H2), inhibits apoptosis mediated by these receptors." (PMID 29375318, 2017). "It is now well-established that netrin-1 elicits chemoattractant guidance by binding to its canonical receptors deleted in colorectal cancer (DCC) and neogenin, or chemorepellant guidance by binding to the DCC/uncoordinated (Unc5) A–D receptor complex." (PMID 29017609, 2017). "While at least eight netrin receptors have been characterized in the vascular system, netrin-1 function is mainly mediated by two families of receptors: DCC (deleted in colorectal cancer) and UNC5 (uncoordinated-5) families." (PMID 29059224, 2017). "Netrin-1, a multifunctional axon guidance cue, elicits axon outgrowth via one of its receptors deleted in colorectal cancer (DCC) in several types of neurons, including cerebral cortical neurons of embryonic mice." (PMID 29041904, 2017). "The interaction between the secreted ligand Netrin-1 and its receptor Deleted in Colorectal Carcinoma (DCC) is thought to control midline attraction of crossing axons." (PMID 28240285, 2017).
colorectal cancer (continued). "Netrin-1 blocks apoptosis induced by the prototypical dependence receptors deleted in colorectal carcinoma and uncoordinated phenotype-5." (PMID 28174720, 2016). "DCC (netrin-1), originally discover in colorectal cancer, is characterized as a candidate tumor suppressor gene that encodes the netrin 1 receptor, a member of the immunoglobulin superfamily of cell adhesion molecules." (PMID 26602921, 2015). "Beside its role as a major axonal guidance molecule in mammalian CNS development, netrin-1 also exerts anti-apoptotic effects via binding to one of its major dependence receptors, deleted in colorectal cancer (DCC), thereby driving tumorigenesis." (PMID 24647424, 2014). "Netrin-1 and its receptors, deleted in colorectal cancer and uncoordinated gene 5H (which includes UNC5H1-4/UNC5A-D) are highly expressed in the colon epithelial cells as well as immune cells." (PMID 24720832, 2014). "The guidance cue netrin-1 organizes neuronal networks by attracting or repelling cellular processes through DCC (deleted in colorectal cancer) and UNC-5 homologue (UNC5H) receptors, respectively." (PMID 20628609, 2010). "The importance of Sema6A expression in pontine nuclei is, however, called into question by analyses of mutants in Netrin-1 or its receptor, deleted in colorectal cancer (DCC)." (PMID 19063725, 2008). "Recent studies report serum netrin-1 a novel biomarker in colorectal cancer and lung cancer." (PMID 38638604, 2024). "Moreover, the treatment of colorectal cancer cells with NTN-1 and with the adipocyte-derived secretome obtained from patients with obesity increased the migration of colorectal cancer cells." (PMID 36831381, 2023). "In addition, NTN1 has been demonstrated to enhance the progression of colorectal cancer by releasing anti-apoptotic signals through the NF-kappaB pathway in individuals with inflammatory bowel disease." (PMID 37345154, 2023). "During development, multiple guidance cues can control the guidance of axons to their specific targets and help establish functional neural circuits, such as netrin‐1 (NTN‐1)/deleted in colorectal carcinoma (DCC), Slit3/robo, Semaphorin5A/plexin, and ephtinB/ephB pathways." (PMID 36852451, 2023). "Netrin-1 could bind to the receptors deleted in colorectal cancer (DCC), neogenin-1(Neo-1), or uncoordinated (UNC5) and then participate in the formation of various chronic pain conditions." (PMID 35966013, 2022). "In colorectal cancer, CAFs can control cancer cell plasticity by Netrin-1." (PMID 36319622, 2022). "After exosomes were cocultured with colorectal cancer tumor circulating T84 cells, the expression of Netrin-1 and CD146 was upregulated, the expression of miR-329-3p was downregulated, the proliferation and migration ability of T84 cells were enhanced, and EMT occurred." (PMID 36093435, 2022). "This study was based on the notion that the interaction of netrin-1 with its receptor deleted in colorectal carcinoma (DCC) might involve an additional co-receptor, since netrin-1 protein only co-immunoprecipitate with DCC if cross-linked." (PMID 35910389, 2022). "Chemoattractive signaling effected, for instance, via Netrin-1 through its receptors deleted in colorectal cancer (DCC) and Down’s syndrome cell adhesion molecule (DSCAM), is responsible for the attraction of commissural axons toward the midline in the spinal cord." (PMID 33771901, 2021). "In addition, DSCAM and deleted in colorectal carcinomas (DCC) are both receptors of netrin-1, which serves as an important axon guidance cue during neural development." (PMID 34136475, 2021). "Finally, we found that Netrin-1/Deleted in Colorectal Cancer (Dcc) proteins acted downstream of Nova2 to suppresses neuronal migration." (PMID 32271715, 2020).
colorectal cancer (continued). "Indeed, our own studies have shown that Netrin-1/Deleted in Colorectal Cancer (DCC) signaling triggers exocytosis through the SNARE Syntaxin-1 (STX1)." (PMID 29912942, 2018). "Paradisi revealed that NF-κB regulates netrin-1 expression in human colorectal cancer cells." (PMID 26393880, 2015). "As netrin-1 and its receptor deleted in colorectal cancer (DCC) are important regulators in neuronal and vascular activities, the present study attempted to explore whether netrin-1 and DCC are involved in the neuroprotection of stem cell-based therapies in a rat ischemic stroke model." (PMID 29017609, 2017). "A preliminary set of data has shown that overexpression of netrin-1 is only rarely associated with human colorectal cancer –7% of the tested tumours – therefore suggesting that gain of netrin-1 or loss of the receptor does not represent a similar selective advantage." (PMID 15956977, 2005). "MDSCs express a receptor for netrin-1, and netrin-1 enhances the immunosuppressive function of MDSCs through adenosine receptor 2B (A2BR), thereby promoting the development of colorectal cancer." (PMID 39100676, 2024). "In colorectal cancer, IL34 has been shown to regulate the modulators Netrin-1 and b-FGF in colorectal CAFs, thereby influencing the behavior of colorectal cancer cells." (PMID 38081923, 2023). "Collagen triple helix repeat containing 1 (CTHRC1) embedded in the Wingless and Int-1/Planar cell polarity (WNT–PCP) pathway, Netrin-1 (NTN1), and deleted in colorectal carcinoma (DCC) provides for SC migration." (PMID 35408800, 2022). "Netrin 1 (NTN1) and deleted in colorectal carcinoma (DCC) are crucial for remodelling of the interhemispheric fissure (IHF), corpus callosum (CC) and hippocampal commissure (HC) formation." (PMID 33871356, 2021). "One of these molecules, Netrin-1, and its receptor, DCC (deleted in colorectal cancer), has profound effects, in laboratory animals, on the adolescent expansion of mesocorticolimbic pathways, particularly dopamine." (PMID 31659271, 2020). "An imbalance in netrin-1 and DCC levels have been cited extensively, where the DCC chromosomal region have been reported to be frequently deleted in colorectal cancer, resulting in low DCC expression and thus cell survival." (PMID 29854303, 2018). "Throughout this journey, PNs express the Ntn1 receptor Deleted in Colorectal Carcinoma (DCC) and are exposed to Ntn1 produced in the floor plate (FP) and ventricular zone." (PMID 29444422, 2018). "The cellular response to Netrins is dictated by its receptors: deleted in colorectal cancer (DCC) and perhaps Neogenin enable attraction to Netrin-1, while Unc5 proteins, in some cases in conjunction with DCC, elicit repulsion from Netrin-1." (PMID 26633881, 2015). "Conversely, dMNs express the netrin receptor deleted in colorectal carcinoma (DCC) and are repelled away from the midline expressing netrin 1 (NTN1)." (PMID 25346659, 2014). "In addition, the expression levels of neuropilin 1 and neuropilin 2, receptors for Sema3A, and Neogenin and deleted in colorectal cancer (DCC), receptors for Netrin-1, were evaluated by RT-qPCR." (PMID 36986209, 2023). "Notably, netrin 1 (NTN1) and unc-5 netrin receptor D (UNC5D) form a complex with deleted in colorectal cancer, netrin 1 receptor (DCC) downstream in the NHLH2 pathway, and all three of them are expressed in both testis and brain samples." (PMID 33731013, 2021). "Supporting this, FEZ1 colocalizes with VAMP2 in developing hippocampal neurons and forms a separate complex with deleted in colorectal cancer (DCC) and Syntaxin-1 (Stx1), components of the Netrin-1 signaling pathway that are also involved in regulating axon and dendrite development." (PMID 33771901, 2021).